MMP11 (matrix metallopeptidase 11)
Diseases named in the same sentence as MMP11 in open-access papers (continued):
Sharing a sentence is not in itself a finding about the gene and the disease.
tumor (continued). "The MMP11 rs28382575, rs131451, and rs738792 polymorphisms may potentially provide as tumor markers in UCC treatment or predictors for UCC susceptibility and prognosis." (PMID 31940762, 2020). "So far, tumor-promoting effects of adipocytes are linked to their secretion of adipokines, hormones, and growth factors including matrix metalloproteinase 11 (MMP11), IL-6, IL-1β into the surrounding TME, which collectively enhance the migration and invasion capacity of cancer cells." (PMID 28929459, 2018). "Of note, among the genes implicated in prostate carcinogenesis and resistance to therapy, such as matrix metalloproteinase (MMP)-11, androgen receptor, and interleukin (IL)-17 receptor beta, were genes coexpressed by tumor-associated fibroblasts and tumor cells." (PMID 29380085, 2018). "Furthermore, MMP11 expression, which is also named stromelysin-3 and is correlated with cell migration, tissue morphogenesis, and apoptosis during the development and invasion of tumor cells, is linked to aggressive characteristics of PTC." (PMID 29137300, 2017). "However, other studies have demonstrated an association with MMPs and advanced tumor stage, high grade tumors and metastasis, as well as a role for MMP11 as a serum marker in GC disease." (PMID 24321518, 2013). "Similarly to other studies, our data show that MMP-11 (Stromalysin-3) was preferentially expressed by peritumoral stromal cells and that high levels of MMP-11 were associated with tumour progression and poor prognosis." (PMID 17342087, 2007). "Moreover, we analyzed the relationship between the tumor mutation burden and MMP11 expression." (PMID 39239548, 2024). "Therefore, we proposed that MMP11 could cause tumor cell immune escape in EGFR-mutant LUAD by modifying the immune microenvironment." (PMID 36756152, 2023). "Also, in the clinicopathological and survival analyses, upregulated MMP11 was significantly associated with a higher tumor stage (p = 0.003), a shorter OS (HR = 1.23, p = 3.71 × 10−2), a shorter PFS time (HR = 1.33, p = 2.15 × 10−3), and a shorter RFS time (HR = 1.24, p = 1.71 × 10−3)." (PMID 34804973, 2021). "Hence, MMP-11 gene expression seems to be associated with tumour progression." (PMID 20160732, 2010). "Unlike most MMPs that degrade ECM proteins in the extracellular space, MMP11 is activated intracellularly and modifies the tumor microenvironment, promoting cancer cell survival, invasion, and immune evasion." (PMID 40843631, 2026). "Recent work has described a role for MMP11 in epithelial migration specifically in IP epithelial cells, suggesting a role for MMP11 in tumor microenvironment remodeling, which is crucial for malignant transformation." (PMID 40843631, 2026). "We discovered that NHDC exhibits tumor-suppressive effects against PCa for the first time, identifying MMP11 as a key mechanistic mediator." (PMID 41001131, 2025). "Subtype 2 exhibited significantly higher stromal and immune scores, ESTIMATE scores, MMP11+ mCAF signature scores, and proportions of MMP11+ mCAFs compared to Subtype 1, along with notably lower tumor purity." (PMID 40552583, 2025). "Future studies should consider genetic perturbation strategies, such as CRISPR/Cas9‐mediated knockout or RNA interference, combined with lineage tracing, to more precisely delineate the role of BMP2 signaling in MMP11+ mCAF‐mediated tumor progression." (PMID 40552583, 2025). "Among these, matrix metalloproteinase (MMP) family members—including MMP1, MMP3, MMP9, and MMP11—exhibited significant upregulation, consistent with their established roles in promoting tumor invasiveness." (PMID 40361356, 2025). "Crucially, our study provides the first experimental evidence of NHDC’s anti-tumor effects against PCa cells in vitro, potentially mediated through MMP11 suppression." (PMID 41001131, 2025).
tumor (continued). "It is well established that MMP-2, MMP-9, and MMP-11 contribute to the remodeling of the tumor microenvironment (TME) in gastric cancer through both structural and functional mechanisms." (PMID 40906383, 2025). "Mouse experiments confirmed that BMP2 promotes tumor progression, MMP11 expression, and angiogenesis." (PMID 40552583, 2025). "The role of MMP11 in tumor development is further supported by its increased expression in PCa compared to normal tissues and even higher expression in metastases in the MSKCC dataset (n = 179)." (PMID 40122809, 2025). "In fibroblasts, ECM regulators such as LOX and MMP11 reinforce tumor-supportive stroma and impede immune infiltration." (PMID 41164190, 2025). "MMP11 targeting in other types of cancer has already been identified as a potential therapeutic strategy due to its role in tumor progression and metastasis." (PMID 40122809, 2025). "Given the established links between neoantigens, tumor mutational burden (TMB), and microsatellite instability (MSI), we observed significantly higher TMB and MSI in the MMP11-high group, suggesting enhanced potential for immunotherapy responsiveness." (PMID 40607407, 2025). "Therapies targeting matrix metalloproteinase 11 (MMP11) can promote cell-mediated immune responses, resulting in anti-tumor effects." (PMID 39722065, 2025). "The DEGs included genes involved in cell proliferation and migration (e.g., COL11A1), tumor‐promoting factors that degrade the extracellular matrix (e.g., MMP11), as well as immunosuppressive (TGFB1) and proinflammatory responses (TNFRSF6B, IFNGR2, GSDMB)." (PMID 40952312, 2025). "Our study further validates these findings, showing that NHDC similarly suppresses PCa cell proliferation, migration, and invasion while inhibiting the expression of the tumor progression factor MMP11." (PMID 41001131, 2025). "An intriguing finding in our study is the observation that, during tumor progression, the MMP11+ mCAFs subpopulation exhibits an inverse trend compared to the IGLC1+ CAFs subpopulation, which is associated with a better prognosis." (PMID 40552583, 2025). "The proportion of MMP11+ mCAFs progressively increased with tumor progression and was predominantly enriched in high‐grade tumors." (PMID 40552583, 2025). "We found that high expression of MMP11 and MYL9 genes was negatively correlated with tumor mutation burden (TMB) scores (p < 0.05)." (PMID 41009818, 2025). "We further applied the CIBERSORT deconvolution algorithm to estimate the proportion of MMP11+ CAFs in TCGA datasets corresponding to these cancers and explored their relationship with tumor progression." (PMID 40552583, 2025). "For example, genetic manipulation of DEFA3, MMP11, or MYL9 in APC Min/+ mice would directly reveal their causal roles in tumor initiation, progression, or metastasis." (PMID 41009818, 2025). "Collectively, these data position MMP11 as a promising dual-functional target: Immunogenicity: Directly eliciting anti-tumor CTL responses; Neoantigen Enrichment: Enhancing TMB/MSI-driven immune recognition." (PMID 40607407, 2025). "Proportional analysis revealed that MMP11+ mCAFs were more abundant in tumor tissues compared to adjacent normal tissues." (PMID 40552583, 2025). "Concurrently, we observed marked upregulation of multiple pro-tumor factors, including MMP-11, IL-6, IL-1β, CCL5, and CCL2." (PMID 41276817, 2025). "IF staining of tumor sections showed that MMP11+ mCAFs are spatially adjacent to endothelial cells, providing anatomical evidence for potential paracrine signaling." (PMID 40552583, 2025). "With the exception of the immune score, the stromal and ESTIMATE scores were found to be statistically significant, and higher scores were observed in MMP11 tumor tissues." (PMID 39239548, 2024). "Several studies have reported that MMP11 participated in cancer development by inhibiting apoptosis and promoting migration, invasion and metastasis of tumor cells." (PMID 39272712, 2024).
tumor (continued). "Similar differences with statistical significance existed between the high and low MMP11 groups, demonstrating the remarkable interactions between MMP11 and tumor immunology." (PMID 39239548, 2024). "We discovered that MMP11 expression was strongly correlated with age, tumor node metastasis (TNM) classification, and stage." (PMID 39239548, 2024). "Single-cell RNA-sequencing of cell populations from the NIH dbGaP in the PDAC TME indicates that MMP3 is expressed in the tumor and MMP11 is expressed in the stromal populations." (PMID 38619621, 2024). "Among the patients (aged 31–89, median 60, with average tumor size of 15.7 mm), MMP-11 staining was observed in half of the cases." (PMID 38438841, 2024). "Due to its unique structure, MMP11 plays a distinct role in tumor development compared to other MMPs." (PMID 39239548, 2024). "Tumor cells can release MMP11 in an autocrine manner, which significantly impacts the tumor microenvironment and interacts with it to promote tumors' malignant growth." (PMID 39239548, 2024). "Downregulation of MMP11 stimulates cancer cell apoptosis and limits tumor cell invasion and metastasis." (PMID 39684767, 2024). "This analysis showed that the presence of UPP1high tumor cells was significantly positively associated with FOXP3+ regulatory T cells (Tregs), MMP11+ cancer-associated fibroblasts (CAFs), LAG3 + PDCD1 + CD8+ exhausted T cells, and M2-like SPP1+ macrophages." (PMID 38331898, 2024). "Our findings highlight the presence of MMP-11 in the tumor stroma, where it likely exerts its functional effects." (PMID 38438841, 2024). "MMP-11 is involved in extracellular matrix remodeling and contributes to tumor growth, invasion, and metastasis." (PMID 38627864, 2024). "The results showed that the proportion of MMP11+ CAFs-like fibroblasts was significantly higher when co-cultured with UPP1-overexpressing tumor cells than with control cells." (PMID 38331898, 2024). "We also considered the potential cross-reactivity of the MMP-11 antibody with other MMPs, such as MMP2 (gelatinase A), MMP9 (gelatinase B), and MMP14 (membrane-type 1 MMP), which are commonly associated with tumor cells." (PMID 38438841, 2024). "MMP-11, primarily present in tumor-surrounding stromal cells, correlates with tumor grade and uPA levels." (PMID 38438841, 2024). "Pharmacological inhibition of MMP11 should be a serious objective to achieve slow tumor growth in the early phase of its development, as it targets multiple processes involved in tumorigenesis." (PMID 37445827, 2023). "A positive correlation between MMP-9 (gelatinase B) and MMP-11 (stromelysin-3) proteins and increased tumor aggressiveness has been revealed." (PMID 36793738, 2023). "To demonstrate that the transcriptomic profiles during AOIs selection reflected the histological definition of tumor invasive margin, we evaluated the mRNA levels of MMP1, MMP7, and MMP11 in tumor invasive margin, tumor center, and adjacent normal areas." (PMID 37964075, 2023). "MMP11 is produced by peritumoral stromal fibroblasts, it regulates early tumor invasion, implantation and expansion and it prevents apoptosis of early cancer cells." (PMID 38156105, 2023). "Subcluster mFibro accounted for the majority of the fibroblast populations in tumor tissue and expressed a high level of COL1A1, MMP11, FN1 and POSTN, which were associated with collagen secretion and extracellular matrix modeling." (PMID 37265785, 2023). "Tumor cells can release MMP11 in an autocrine manner, actively altering the tumor microenvironment to interact with it to adapt to its malignant biological behavior." (PMID 36756152, 2023). "Among 439 studies of MMP11, 107 studies showed significant differences and among 97 studies, 15 tumor mRNA expression levels were higher than normal tissues." (PMID 36941602, 2023). "MMP11 has been shown to be upregulated in 15 different solid cancer types and is known to facilitate tumor invasion." (PMID 36743421, 2023).
tumor (continued). "Differences in MMP11 expression in tumor tissues vs. normal tissues were explored using bioinformatic analysis techniques." (PMID 36756152, 2023). "Paradoxically, MMP11 has also been suggested to act as a tumor suppressor by inhibiting the metastasis of some tumors." (PMID 38156105, 2023). "It is worth noting that MMP-11 plays a significant role during tumor desmoplasia and constitutes a molecular link between obesity and cancer." (PMID 38203373, 2023). "MMP11, a matrix metalloproteinase, is known to degrade the extracellular matrix, potentially escalating tumor invasion and metastasis." (PMID 37702857, 2023). "Due to its special structure, MMP11 has a unique role in tumor development compared to other MMPs molecules." (PMID 36756152, 2023). "Specifically, MMP9, MMP13, MMP11, and CEMIP were positively associated with the tumor immune microenvironment, while SLPI, SLC2A1, SERPINB5, HK2, CEACAM6, and CEACAM5 were negatively associated with the tumor immune microenvironment." (PMID 37234801, 2023). "Conversely, S100A11, p-AKT, MMP11, and N-cadherin expression was higher in tumor tissues than in adjacent normal tissues." (PMID 37166978, 2023). "After analysis, we found that samples with different MMP11 expression profiles in EGFR-mutant LUAD had different infiltration of immune cells in the tumor parenchyma." (PMID 36756152, 2023). "On the other hand, in animal models, MMP-11 has a protective effect on tumor growth and metastasis at more or less advanced stages." (PMID 38203373, 2023). "Upon histopathological analysis, along with histopathological classification and staging, the degree of CD4, CD8, and CD163 cell infiltrations and expressions of interleukin-6 and matrix-metalloproteinase-11 (MMP-11) in the primary tumor were assessed." (PMID 36010928, 2022). "MMP-11 is located mainly in the adipose tissue in the proximity of a tumor, being correlated with adipogenesis processes." (PMID 35163727, 2022). "The most important MMP is MMP11, which is overexpressed in tumours and participates in the proliferation and malignant development of tumour cells." (PMID 36105798, 2022). "The results showed that CAFs in P-LNs were associated with the high expression of NFIB, IGLC2, IGHG4, C7, and CCL19, while CAFs in tumor 3 had high expression of DIO2, LGALS1, WNT5A, NEAT1, and MMP11 in the tumor." (PMID 36569924, 2022). "Only the GLCM contrast showed a positive relationship with MMP-11 expression in the tumor tissue, revealing significantly higher values in patients with grade 3 than in those with grades 0 and 1 (p < 0.05)." (PMID 36010928, 2022). "Especially relevant was our finding that the combination of tumor budding grade with MMP-11 expression by stromal MICs was significantly and independently associated with the highest prognostic accuracy." (PMID 33669393, 2021). "After that, xenograft formation assay revealed that the tumor volume and weight were declined in the presence of circ-MMP11 downregulation or lapatinib treatment, hinting at the repression role of circ-MMP11 knockdown or lapatinib treatment on tumor growth." (PMID 34295807, 2021). "As a result, cancer testis antigen (CTA), activated dendritic cells (DC) and tumor-infiltrating lymphocytes (TILs) were decreased in patients with high MMP-11 expression compared to those with low MMP-11 expression (p = 0.03, 0.009 and 0.012, respectively)." (PMID 34038440, 2021). "In the clinicopathological analyses, upregulated MMP11, MMP14, MMP16, MMP17, MMP19, and MMP23B were significantly associated with a higher tumor stage." (PMID 34804973, 2021). "In this study, MMP11 was significantly upregulated in tumor, both in public database (Oncomine and GEPIA) and in our samples." (PMID 34804973, 2021). "In BC, numerous subtypes of MMPs containing MMP1, MMP7, MMP9 and MMP11 have investigated a positive correlation between increased levels of MMPs and tumour progression." (PMID 34142438, 2021).
tumor (continued). "Our present findings demonstrated that MMP11 exerted tumor-promotive functions on the progression of HCC." (PMID 33836753, 2021). "Conversely, expression of MMP2 and MMP11 was found to be reduced in cases with advanced tumor stages (T3–T4) and nodal metastasis (N+)." (PMID 33578082, 2021). "In silico cytometry, there was a decrease of cancer testis antigen and low tumor infiltrating lymphocyte in patient with high MMP-11 expression: activated dendritic cell, CD8+T cell, CD4+ memory T cell, and memory B cell." (PMID 34038440, 2021). "We believe that medical oncologists and researchers will be interested in the role of MMP-11 in promoting tumor invasion by ECM breakdown and that these results will contribute to designing future experimental studies." (PMID 34038440, 2021). "Then, we found that the HCC tissues displayed markedly decreased let-7a-5p expression levels accompanied by elevated MMP11 protein expression relative to adjacent non-tumor tissues." (PMID 33836753, 2021). "To address the metabolic role of MMP11 in tumors, we measured the expression of key metabolic genes in tumor samples." (PMID 32825455, 2020). "MMP11 is expressed in stromal cells and favors cancer cell survival and tumor progression through cleavage of collagen VI29." (PMID 32577501, 2020). "The alteration of these genes suggests that in the presence of MMP11, tumor cells have a decrease in mitochondrial respiration." (PMID 32825455, 2020). "The increased expression of MMP-11, both in epithelial and tumor stromal cells, suggests that neoplastic cells diffusely produce factors that induce fibroblasts to synthesize this protease." (PMID 32813775, 2020). "MMP-11 is called stromelysin 3, which plays a vital role during tumor migration, invasion, and metastasis." (PMID 32664553, 2020). "MMP-11 (stromelysin 3) plays an important role in tissue remodeling and is seen in tumor growth and metastases." (PMID 32813775, 2020). "MMP11 promotes tumor cell survival and significantly increases cell proliferation in tumor samples from PyMTTg; MMP11Tg mice as compared to control PyMTTg; MMP11WT animals, thereby accelerating tumor growth." (PMID 32825455, 2020). "In conclusion, we report that MMP11 inhibits cell death and promotes tumor growth by activating the IGF1/AKT/FoxO1 pathway in the MMTV-PyMT mouse model of mammary gland tumor." (PMID 32825455, 2020). "Our results show that MMP11 affects body weight and tumor incidence in MMTV-PyMT mice at an early stage of tumor development." (PMID 32825455, 2020). "Together, these data demonstrate that MMP11 accelerates MMTV-PyMT transgenic mice tumor development and growth at early stage." (PMID 32825455, 2020). "Both GOF and LOF models support roles for MMP11, favoring early tumor growth by increasing proliferation and reducing apoptosis." (PMID 32825455, 2020). "In the presence of MMP11, the Warburg-like effect is increased in tumor samples through a metabolic reprogramming." (PMID 32825455, 2020). "Matrix metalloproteinase 11(MMP11) is responsible of serpins cleavage and so it stimulate the development of tumor." (PMID 31288815, 2019). "VCAM1 is one of five genes (CXCL12, MMP2, MMP11, VCAM1, and MME), which were associated with tumor progression, angiogenesis, and metastasis." (PMID 31731625, 2019). "We also detected the expression of MMP11 in GC tumor tissues and matched normal tissues, we found that MMP11 was significantly increased in GC tumors compared with matched nontumoral tissues, and also elevated in metastatic compared with non-metastatic tumors." (PMID 31595150, 2019). "Through the regulation of MMP11 expression, suppression of exosomal miR-139 promoted the pro-tumor activity of CAFs in GC." (PMID 31595150, 2019). "Recently, the development of MMPIs has moved away from general MMPIs towards specific inhibitors for MMP1, gelatinases, MMP11 and specific cancers or stages of tumor progression." (PMID 31514474, 2019).